S100A9 (S100 calcium binding protein A9)
Diseases named in the same sentence as S100A9 in open-access papers (continued):
Sharing a sentence is not in itself a finding about the gene and the disease.
tumor (continued). "Although these slight differences in expression levels could be seen, we conclude that the differential expression of S100A4 and S100A9 in splenic CD11b+ cells remains also during inflammatory disease or tumor challenge." (PMID 23667563, 2013). "Interestingly, both RAGE and TLR4 have been shown to play a role in the control of tumor growth in different systems, and it has also been shown that inhibition of S100A9/TLR4 interactions can inhibit tumor growth." (PMID 23667563, 2013). "Interestingly, S100A4 and S100A9 are expressed by distinct CD11b+ subpopulations both in healthy animals and in animals with either inflammatory disease or tumor burden." (PMID 23667563, 2013). "The same study showed that up-regulation of S100A8 and S100A9 by tumor- derived factors might represent one major mechanisms by which abnormal DC differentiation is established in cancer." (PMID 23166536, 2012). "Furthermore, we addressed the correlation between the number of S100A9-positive cells in tumor tissues and the clinicopathological features." (PMID 22838504, 2012). "Using Western blot the down-regulation of S100A9 could also be seen in tumor-derived CD11b+Ly6C+G+ cells at the protein level, although not as marked as at the RNA level." (PMID 23234398, 2012). "The rational for this approach was that critical mediators should show the same deviation in TLR4−/− and S100A9−/− animals compared to C57BL/6 controls if they could be involved in the observed in vivo effect on tumor growth regulation." (PMID 22470535, 2012). "We next wanted to investigate the effect of tumor inoculation on S100A9 expression." (PMID 23234398, 2012). "Through the production of VEGFA, TGFβ, and tumor necrosis factor-α (TNFα), tumor cells enhance the expression of the chemoattractants S100A8 and S100A9 in lung endothelium and myeloid cells, which in turn promote tumor cell homing and adhesion to the metastatic site." (PMID 22482059, 2012). "However, when cells with the same surface phenotype were isolated from the tumor tissue, the S100A9 RNA expression was lower compared to the corresponding splenic cell populations." (PMID 23234398, 2012). "Thus, the reduced tumor growth observed in S100A9−/− and TLR4−/− animals correlate with low TGFβ RNA expression in splenic CD11b+ cells." (PMID 22470535, 2012). "S100A9 has also been shown to be involved in the process of tumor metastasis." (PMID 23234398, 2012). "Also, the S100A9 expression in this cell population was down-regulated in the granulomas, as observed in tumor tissue." (PMID 23234398, 2012). "To directly test whether the S100A9/TLR4/RAGE interaction was important for EL4 tumor growth in vivo we therefore treated EL4 inoculated animals with 30 mg/kg ABR-215050 and compared to control animals." (PMID 22470535, 2012). "Also, compared to normal prostate in mice or adjacent normal prostate tissue in human biopsies, S100A9 expression was found mostly in tumor tissue." (PMID 22470535, 2012). "Indeed, many of the key soluble factors implicated in defining tumor-associated niches, such as VEGF, PlGF, SDF-1α, S100A8, S100A9, SAA3, TNF-α, and TGF-β are HSPG-binding proteins." (PMID 21698156, 2011). "S100-A9 is mainly expressed by macrophages in acutely inflamed tissues and in chronic inflammation, detected in peripheral blood leukocytes, in neutrophils and granulocytes infiltrating the tumor tissue." (PMID 21760917, 2011). "These were Defcr4, S100A9, Igfbp5, Slc30a2 and Lgr5 (leucine-rich repeat containing G protein coupled receptor 5) which were up-regulated and Mptx, Slc26a3, Retnla, Muc2 and Hpgd (hydroxyprostaglandin dehydrogenase 15) which were down-regulated in tumours." (PMID 20459814, 2010). "Interesting, "M2-like" tumor infiltrating myeloid-derived suppressor cells (MDSCs) is a cell population with a phenotype similar to M2 macrophages expressing high levels of arginase-1 and S100A9 protein." (PMID 20470445, 2010).
tumor (continued). "Blocking S100A8 and S100A9 expression in the premetastatic stage could prevent this permissive niche from being formed and thus inhibit the migration of tumor cells." (PMID 19292913, 2009). "The molecular mechanisms of this phenomenon remain largely undefined, however, a recent study demonstrated that tumour-induced and Stat3-dependent up-regulation of S100a8 and S100a9 proteins in myeloid precursor cells are necessary for the accumulation of Gr1+CD11b+MDSCs." (PMID 19426472, 2009). "Importantly, dramatically decreased levels of pro-inflammatory mediators (e.g. Ptgs2, S100a8, S100a9, and macrophage inflammatory proteins) and reduced numbers of infiltrating immune cells accompanied impaired tumour formation in Rage-/- animals." (PMID 19426472, 2009). "Moreover, Sinha and colleagues found that S100a8/S100a9 produced and secreted by tumour cells binds to Rage on MDSCs and promotes their migration and accumulation through NF-κB signalling pathways." (PMID 19426472, 2009). "S100A8 and S100A9 are chemoattractant proteins that can promote the recruitment of immune-suppressive immune cells into tumor niches, and their detection here may therefore be consistent with this notion." (PMID 19536297, 2009). "In addition, S100A9 reduces tumor cell autophagy through MAGE-A3." (PMID 41173834, 2025). "S100A9, which we found up-regulated in pT1-HG biopsies, was identified as a protein associated with iNOS activity, and it is also involved in the regulation of signal transduction, such as SOD2, APOA1, HSP90, HSPA5, HINT1, MYDGF, and SerpinB3, and in immunomodulation in tumor microenvironments." (PMID 41441336, 2025). "In vitro, Paquinimod reduced the chemotactic response of Ly6Chigh myeloid cells to recombinant S100A9 and CT26 tumor supernatant, strongly suggesting that Paquinimod might promote tumor growth through blocking chemotactic signals from tumor, through binding to S100A9." (PMID 39497822, 2024). "Previous studies have suggested that a slightly higher extracellular S100A9 level can promote the development of tumors, but a higher S100A9 level can induce apoptosis of tumor cells; The concentration of S100A9 in cells may affect the epithelial-mesenchymal transformation signal." (PMID 39137310, 2024). "In addition, angiogenesis and EMT pathways were also significantly activated in patients with high S100A9 expression, suggesting that S100A9 may be involved in UC-related tumor development." (PMID 38448514, 2024). "Taken together, investigating the pleiotropic effects of S100A9 is critical, and appears to require multiple targeting strategies and, a clearer understanding of the contribution of various signaling pathways in the initiation and maintenance of anti-tumor responses." (PMID 39497822, 2024). "The knockdown of advanced glycosylation end product-specific receptor (AGER), the receptor of S100A9, eradicates the NF-κB-mediated pro-tumorigenic effects of S100A9, suggesting that S100A9 controls the crosstalk between tumor cells and TAMs and could be a potential target for treating HCC patients." (PMID 38397187, 2024). "In addition, we found that the expression at the RNA level of THBS4 together with S100A9 is an independent prognostic signature that remains predictive of metastasis despite confounding factors that include patient age, tobacco consumption and tumor stage." (PMID 38022675, 2023). "Taking into account the evidences of S100A9 as a mediator of resistance of BMs to radiotherapy, the inhibition of the S100A9–RAGE axis could be a novel approach to restore the sensitivity to this treatment in cancer patients with brain dissemination of the tumor." (PMID 36652782, 2023). "Accordingly, tumor cells were extracted for subpopulation analysis, and the identified malignant cells clustered into eleven subclones: BRCA_SRGN, BRCA_SLC39A6, BRCA_ITGB3, BRCA_PECAM1, BRCA_PPP1R1B, BRCA_VCAM1, BRCA_ICAM1, BRCA_S100A9, BRCA_GLUL, BRCA_TASTD2 and BRCA_AGR3." (PMID 37626402, 2023).
tumor (continued). "However, S100A9 functions as both a tumor suppressor and a tumor promoter." (PMID 37686186, 2023). "Interestingly, while cancer biomarkers are often sought exclusively among cancer cell proteins, S100A9 was traced back to components of the tumour microenvironment (TME), specifically in macrophages and neutrophils at the tumour-liver interface in replacement lesions." (PMID 39516397, 2023). "The molecular mechanism of pro- and anti-tumor properties of S100A9 is still unknown." (PMID 35123499, 2022). "The tumor growth could also be significantly minimized by CRISPR-Cas9 mediated knockout of S100a9." (PMID 35304461, 2022). "Interestingly, signal transduction proteins S100A8 and S100A9 upregulated in exosomes of poor responders were previously proposed as CRC tumor-specific exosomal markers, involved in migration, leucocyte recruitment, tumor-promoting inflammation, and formation of premetastatic niches." (PMID 35205741, 2022). "It was indicated that S100A9 protein secreted by myeloid cells within primary cancers and metastatic sites promotes the accumulation of more myeloid cells, which plays an important role in modulating tumor progression and the formation of premetastatic niches at metastatic sites." (PMID 34374812, 2022). "S100A9 at high extracellular concentrations could induce the apoptosis pathway in cancer cells, while at lower levels S100A9 seem to promote proliferation of tumor cells." (PMID 35123499, 2022). "Finally, we demonstrated that sgCxcl12 could block the effect of overexpression of S100a9 in the induction of MDSCs and inhibit the tumor growth." (PMID 35304461, 2022). "S100A9 was assumed as a marker of MDSCs, which could recruit MDSCs in tumor microenvironment." (PMID 34045609, 2021). "In addition, S100A9 might indirectly promote tumor growth by promoting MDSC-mediated immune suppression." (PMID 34572138, 2021). "Consequently, S100A9 might control tumor progression by acting either directly on tumor cells or indirectly on the tumor microenvironment." (PMID 34157683, 2021). "In addition to suppressing immunity, CXCL1 and CXCL2 also recruit myeloid cells to produce paracrine factors such as S100A9 and promote tumor cell survival found that silencing CXCL1 can down-regulate NF-κB and mesenchymal cell transformation, and inhibit the growth of human glioma xenograft." (PMID 34630121, 2021). "In the (murine mouse lymphoblastic lymphoma cell line (el4)), tasquinimod, through blockade of the interaction of S100A9 with its membrane receptors TLR4, could inhibit tumor growth, which was associated with reduced expression of transforming growth factor (TGFβ)." (PMID 33801279, 2021). "In addition, Fn-challenged M2-like Mφ conferred CRC cells a more malignant phenotype, showing stronger proliferation and migration characteristics in vitro and significantly enhanced tumor growth in vivo, all of which were partially inhibited when S100A9 was lost." (PMID 34093546, 2021). "In addition, we examined S100A9 expression in NKTCL tumor tissues." (PMID 34045609, 2021). "Interestingly, S100A9 is expressed in both tumor and infiltrating immune cells." (PMID 32793473, 2020). "Consequently, S100A9 could be considered as a pivotal target that gathered upstream signals and produced branches of downstream signaling pathways in the tumor development." (PMID 33203795, 2020). "Therefore, IL-33 may induce chemokines (e.g. Cxcl1), which enhanced the recruitment of myeloid cells secreting S100A9 to promote tumour progression." (PMID 33308251, 2020). "S100A9 knockout mice, which are deficient in their ability to accumulate MDSCs in tumor-bearing hosts, showed significantly reduced MDSC accumulation in the bone marrow along with significant accumulation of tumor-specific CD8+ cells, suggesting a possible CD8+-specific effect of MDSCs." (PMID 33643299, 2020). "However, A-674563 blocked intracellular S100A9-induced tumor growth." (PMID 33203795, 2020).
tumor (continued). "Thus, increased S100A9 was found at the RNA and protein levels after IL-33 treatment, which may provide a pre-metastatic niche that could lead to tumour occurrence." (PMID 33308251, 2020). "Notably, knockdown of S100A8 and S100A9 significantly reduced tumor growth in nude mice." (PMID 32503348, 2020). "Interestingly, recent research indicated that S100A9 could be one marker for circulatory MDSCs, and other studies showed that MDSCs from tumor-bearing mice or peripheral blood in cancer patients express and secrete S100A9 in an autocrine manner." (PMID 31620141, 2019). "However, in the present study, S100A8 and S100A9 did not exhibit an association with RCC tumor grades." (PMID 25673070, 2015). "Indeed, low concentration of S100A9 has been reported to have pro-tumor proliferative effects." (PMID 26431492, 2015). "Thus, DCLK1 may exert influence on immune suppression, tumor microenvironment, and tumor-stromal interactions by modulating S100A9 and NFκB activities." (PMID 25948779, 2015). "Thus, blocking the function of S100A9 by small molecule inhibitors may provide a new approach for the prevention of tumour growth and metastasis." (PMID 24162378, 2014). "Thus, despite plasma levels of < 1 μM, the EPR effect results in intracellular drug concentrations of 2-3 μM, levels several-fold higher than needed for inhibition of endothelial sprouting (IC50 ~ 0.5 μM) or for inhibition of HDAC4 and S100A9 mediated tumor growth." (PMID 25193858, 2014). "Extracellular S100A8 and S100A9 in tumor microenvironment may mainly exert their biological roles in CRC progression, and their secretion to tumor microenvironment may be affected by a variety of factors including tumor cells, stromal cells, and other composition of the tumor microenvironment." (PMID 23637971, 2013). "Furthermore, it has been shown that S100A9 protein is involved in tumour growth." (PMID 23626736, 2013). "Thus, it can be speculated that these cells release S100A9 that via interaction with TLR4 promote tumor growth." (PMID 22470535, 2012). "Thus, S100A9 may prove a valuable target for prevention of the migration of tumor cells to pre-metastatic sites." (PMID 20096140, 2010). "In addition, S100A8/S100A9 could directly induce proliferation of tumour cells via RAGE ligation, as was shown recently in a cell culture model." (PMID 19426472, 2009). "ST analysis showed widespread NETs distribution in tumor tissues, with NETs-related markers S100A8, FUT4, LCN2, S100A9, and HSP3A exhibiting high expression across tissue regions." (PMID 41488283, 2026). "The findings endorse the potential of targeting S100A9 as a therapeutic approach and underscore the effectiveness of tasquinimod in inhibiting SCLC progression, modulating the immune tumor microenvironment, and enhancing overall survival." (PMID 41173834, 2025). "Other proteins present here are involved in matrix remodeling, which can alter tumor invasiveness (MMP13, S100A8, S100A9, and ELN)." (PMID 40699804, 2025). "Our findings indicate that higher S100A9 expression promotes SCLC growth and distant spread by reducing autophagy through MAGE-A3 in tumor cells." (PMID 41173834, 2025). "The interaction between tumor cells and brain cells contributes to a microenvironment that supports BC growth by secreting factors such as ERH, RPA2, S100A9, and nerve growth factor inducible (VGF)." (PMID 39712454, 2025). "MMP9 facilitates ECM degradation, enhancing tumor cell migration, whereas fibronectin supports metastatic cell adhesion, and S100A8/S100A9 contribute to myeloid cell recruitment, generating a pro-inflammatory environment niche." (PMID 40649918, 2025).
tumor (continued). "Tumor-derived lactate drives transcriptional reprogramming (CCL2, ARG1, IL10, S100A9) in TAMs via the ENSA-K63la/STAT3-pY705 axis, promoting an immunosuppressive environment and immunotherapy resistance." (PMID 39883522, 2025). "Given their established roles in pre-metastatic remodeling, PMN lung tissue samples from days 11 and 14 post-tumor induction were analyzed for MMP9, fibronectin, and the chemoattractant cytokines S100A8 and S100A9 using ELISA assays." (PMID 40649918, 2025). "Normal tissues exhibited higher levels of S100A9, FTCD, POF1B, IL7R, and MYO1E, whereas tumor tissues showed increased expressions of SPINK1, CXCL9, AGFG1, and IQGAP3." (PMID 41578779, 2025). "Our results showed that the expression of the S100A9, as well as S100A8, mRNAs were induced in Fusobacterium-high tumor samples." (PMID 40895532, 2025). "S100A9’s capacity to interact with RAGE and TLR4 receptors on tumor and myeloid cells indicates its role in fostering a pro-inflammatory microenvironment." (PMID 41009692, 2025). "To verify the importance of S100A9 signaling on anti-tumor immunity, we injected recombinant S100A9 into CT26 tumors and did indeed observe a significant anti-tumor effect from day 17 onwards." (PMID 39497822, 2024). "When the body is in a pathological state, such as inflammation and tumor, the S100A8 and S100A9 levels are abnormally elevated." (PMID 39575241, 2024). "Extracellularly, S100A8/S100A9 heterodimer fulfils the characteristics of a DAMP and binding with RAGE, through MAPK pathway, contributes to the viability and migration of tumor cells in a concentration-dependent manner." (PMID 39830522, 2024). "Subsequent works have shown that blocking the effect of S100A9, S100A8 or S100A8/A9 in various ways in a tumor setting, can reduce immune suppression and tumor growth and affect the accumulation of myeloid cell populations." (PMID 39497822, 2024). "Two other genes highly correlated with HPV gene expression, S100A9 and PLOD1, are involved in inflammation and tissue remodeling and important for tumor growth, invasion, and metastasis." (PMID 39193365, 2024). "Our results highlighted S100A9 and S100A8 as more-abundant proteins in the superficial tumor samples, in accordance with previous studies." (PMID 39195201, 2024). "Interestingly, the authors find that the anti-tumor effect of Tasquinimod is conserved in TLR4-deficient mice, indicating that Tasquinimod effect might be due to blocking S100A9-signaling through other receptors, or potentially to additional, yet unidentified mechanisms." (PMID 39497822, 2024). "Lastly, both S100A9 and KIF2C, as being an integral part of the tumor microenvironment, have been reported as suitable markers for evaluating immunotherapy response." (PMID 39268460, 2024). "Surprisingly, we found that blocking the extracellular TLR4 signaling from S100A9 using the inhibitor Paquinimod, resulted in increased tumor growth and a detrimental effect on anti-PD-L1 efficacy in the CT26 tumor model." (PMID 39497822, 2024). "Recent discoveries implicate BRCA1, a known tumor suppressor, as essential for regulating the levels of S100A8 and S100A9 in the body." (PMID 39057065, 2024). "Galectin-3, basigin, S100A9, and fibronectin involved in TME–CRC–ECM crosstalk were found to be differently variated in both tumor regions." (PMID 39195201, 2024). "In tumor cells, S100A8 and S100A9 induce phenotypic changes by influencing calcium ion concentrations and other pathways." (PMID 38817853, 2024). "We conclude that Paquinimod inhibits the chemotactic effect of S100A9 on Ly6Chigh cells, as well as reduce the chemotactic effect of CT26 tumor cell supernatant." (PMID 39497822, 2024). "In the tumor array, correlations were observed between S100A8 and S100A4 (R = 0.66), S100A9 (R = 0.62) and S100A10 (R = 0.46)." (PMID 37627239, 2023).